FOXP3 (forkhead box P3)
Diseases named in the same sentence as FOXP3 in open-access papers (continued):
Sharing a sentence is not in itself a finding about the gene and the disease.
autoimmune disease (continued). "Mice lacking FoxP3 protein (scurfin), known as scurfy mice, have no Tregs, defective T cell tolerance and a generalized autoimmune disease that is severe and X-linked lymphoproliferative syndrome." (PMID 34575843, 2021). "Therefore, it is conceivable that gut-derived iTreg cells can reach chronically inflamed tissues in a similar way that activated CD4+CD25+Foxp3+ nTregs are recruited during autoimmune disease development." (PMID 35919733, 2021). "Treg, a subset of CD4+ T cells that can balance Th cells and highly express CD25 and the unique transcription factor forkhead box P3 (FOXP3), has been demonstrated to play a crucial role in the maintenance of immune stability and occurrence and progression of autoimmune diseases." (PMID 35069594, 2021). "In addition, vitamin C has been shown to potentiate Tet activity and increase the stable expression of Foxp3 in iTreg cells via Tet2/3, suggesting a potential clinical application in transplantation and autoimmune diseases." (PMID 34239942, 2021). "Both humans and mice lacking functional Foxp3 suffer severe autoimmune disease and are at high risk of early death due to autoimmune disease caused by a deficiency in TReg cells." (PMID 32670288, 2020). "FOXP3+ regulatory T cells (Tregs) suppress immune responses and are critical for maintaining peripheral tolerance and immune homeostasis, modulating chronic tissue inflammation and autoimmune disease." (PMID 32153577, 2020). "IVIg expands FOXP3+ Treg cells mediated by dendritic cells (DCs) in autoimmune diseases." (PMID 32148437, 2020). "Foxp3+CD4+ regulatory T cells (Treg) constitutes a key event in autoimmune diseases." (PMID 32646440, 2020). "High expression of FR4 and CD73 are shared by anergic CD4+FoxP3- T cells and CD4+Foxp3+ Treg and both molecules are thought to be functionally involved in suppressing immune responses to self-antigens during pregnancy and in autoimmune disease models, in part by allowing the generation of Treg." (PMID 33329540, 2020). "Thus, identification of FoxP3 as a marker and master regulator of Tregs established the possible link between AhR and the regulation of inflammation and autoimmune disease." (PMID 33105907, 2020). "Similarly, Tregs exhibit high levels of expression of the Forkhead Box P3 (FoxP3) gene, regulating self‐reactive immune cells to inhibit autoimmune disease." (PMID 32529780, 2020). "Moreover, distinct FOXP3 splicing variants have been described in humans and variations in their relative expression are present in autoimmune disease patients, suggesting a link between FOXP3 post-transcriptional regulation and autoimmune pathogenicity." (PMID 32153577, 2020). "It is relatively rare to find mutations in FOXP3 itself (IPEX), suggesting that Treg-specific defects in autoimmune disease are likely to result from reduced FOXP3 function or alterations in expression of downstream targets, but not as a result of sequence changes in the FOXP3 gene body." (PMID 33072063, 2020). "Immune dysregulation, polyendocrinopathy, enteropathy, X-linked (IPEX) syndrome is caused by mutations in FOXP3 (Forkhead-Box-Protein P3), a transcription factor that is expressed in a subset of thymic CD4+ T-lymphocytes which are required to maintain tolerance, and prevent autoimmune diseases." (PMID 31799221, 2019). "We and other researchers have reported that in some autoimmune diseases, nTreg may lose Foxp3 expression and convert to T helper cells, such as Th1, Th17 cells." (PMID 30631042, 2019). "The induction and amplification of polyclonal human CD8+CD103+Foxp3+ cells might be a therapeutic strategy to help control autoimmune diseases." (PMID 30915372, 2019). "While this possibility exists, given the plastic nature of T-lineage cells, it may depend on attenuation of FoxP3 expression, or may require an inflammatory trigger, which is more common with autoimmune disease." (PMID 30842776, 2019).
autoimmune disease (continued). "Hence, the balance between FOXP3+ Treg cells and Th17 cells is considered an important factor for treatment of autoimmune diseases and cancers." (PMID 31815635, 2019). "Alteration in glutamate metabolism may also influence Th17 cell differentiation by affecting methylation of Foxp3 in autoimmune disease." (PMID 30800000, 2019). "Given that BBR has been shown to regulate Treg cells by modifying the microbiota in a chemically induced IBD model and to regulate Bcl-2 in an in vitro autoimmune disease model, we next examined the change in the frequency of Foxp3+ Treg cells and the Bcl-2 expression." (PMID 31417110, 2019). "Promoted Treg function driven by sustained Foxp3 expression by daurinol may be a novel treatment strategy for autoimmune diseases that involve impaired Treg function, such as RA and SLE." (PMID 31379809, 2019). "Many molecules have been reported to interact with Foxp3; thus, targeting these molecules directly or indirectly could regulate the function of Treg and improve autoimmune diseases." (PMID 30974919, 2019). "Since Treg cells acquire effector functions through the modulation of transcriptional networks controlling Foxp3 expression, its direct regulation together with the control of its cofactors represent a key immunological strategy for the treatment of autoimmune diseases." (PMID 32117202, 2019). "Other approaches to adoptive Treg cell therapy using either Foxp3-dependent or Foxp3-independent Tregs have been demonstrated in various autoimmune disease mouse models, including SLE, type 1 diabetes, EAE, inflammatory bowel disease, and collagen-induced arthritis (CIA)." (PMID 29535721, 2018). "In addition, alterations in the number and function of CD4+Foxp3+ Treg cells have been reported in most autoimmune diseases as well as in other immune-mediated conditions." (PMID 30116758, 2018). "The lack of Tregs due to the loss of Foxp3 function leads to autoimmune diseases whereas high prevalence of Tregs in the peripheral blood due to the over-expression of Foxp3 causes immunodeficiency." (PMID 28669079, 2018). "The FOXP3 gene (ID: 50943), forkhead box protein 3, a member of transcription factor winged-helix family, is located on chromosome Xp11.23 within the area of AIDs (autoimmune diseases) linkage." (PMID 30229436, 2018). "Therefore, FOXP3 is an appropriate candidate gene to play a role in organ-specific autoimmune diseases, in particular T1D, thyroid autoimmunity and multiple sclerosis." (PMID 30229436, 2018). "However, CD4+Foxp3+ nTreg showed instability in inflammatory conditions and their therapeutic effects on the established autoimmune diseases were sometimes unsatisfactory." (PMID 29441062, 2018). "In human T cells from healthy donors, diesel exhaust particles (DEPs) from low emission diesel engines decreased expression of CD25, a marker for FOXP3+ Tregs, on CD4+ T cells and induced autophagic-lysosomal blockade in vitro which has been associated with pathogenic events of autoimmune disease." (PMID 30574142, 2018). "The concern is that conversion of FOXP3+ Tregs to effector “ex-Tregs” may exacerbate autoimmune disease." (PMID 29312311, 2017). "FOXP3+-Treg-based therapy was safely tested also in the context of autoimmune diseases." (PMID 29075264, 2017). "Additional Treg cell subsets such as CD8+Foxp3+ lymphocytes, Th3 cells, and Tr35 lymphocytes have been described, but they are less well characterized and their possible role in the pathogenesis of autoimmune diseases remains to be elucidated." (PMID 29038617, 2017). "In autoimmune diseases in which Treg are defective, they transiently shift phenotypes from anti- to pro-inflammatory, despite continued expression of the master transcription factor of Tregs, FoxP3." (PMID 29176779, 2017). "Future work is needed to identify whether other NR4A ligands would affect the expression of CD25 and Foxp3 and iTreg cell development and have beneficial effects on chronic inflammatory and autoimmune diseases." (PMID 29208963, 2017).
autoimmune disease (continued). "Since T regulatory cells (Tregs) characterized as CD4+CD25+FoxP3+ (forkhead box P3) cells have emerged pivotal in suppressing autoimmune diseases like type 1 diabetes and others, this review is focused on evaluating the role of Treg defects or dysfunctions in MS- and MG-related autoimmune pathology." (PMID 28599652, 2017). "To investigate the peripheral alterations in FOXP3+ T cell subsets, we performed a detailed immunophenotyping characterisation of cryopreserved peripheral blood mononuclear cells (PBMCs) of different cohorts of patients with autoimmune disease." (PMID 28747257, 2017). "Adoptive transfer of CD4+CD25+FOXP3+ regulatory T cells (Treg cells) has been successfully utilized to treat graft versus host disease and represents a promising strategy for the treatment of autoimmune diseases and transplant rejection." (PMID 28746369, 2017). "There are many evidence that FOXP3 is involved in the pathogenesis of autoimmune diseases." (PMID 27887663, 2016). "Presence of functioning Tregs is required to prevent development of autoimmune diseases, as demonstrated in mice that have undergone day 3 thymectomy, cannot express the Foxp3 transcription factor, or have undergone pharmacological depletion of Tregs after formation of a mature immune system." (PMID 27942026, 2016). "It is currently unclear whether concepts established for efficient murine in vivo Foxp3+Treg induction will be translatable to the human immune system, especially in the context of autoimmune diseases such as T1D." (PMID 26975663, 2016). "The absence of Treg due to mutations in the Foxp3 gene, which encodes for a key transcription factor governing Treg differentiation, causes a multiorgan autoimmune disease in humans known as IPEX syndrome." (PMID 24594700, 2014). "Mice mutated in Foxp3 as well as patients with immune dysregulation polyendocrinopathy, enteropathy, and X chromosome-linked syndrome (IPEX) result in the development of complex autoimmune diseases due to the deficiency of Treg cells." (PMID 25152867, 2014). "Furthermore, the expression of FOXP3 plays an important role in regulating the development and function of Treg and is closely related to autoimmune disease." (PMID 25548591, 2014). "It has already been shown that CD4+CD25+FOXP3+ play a protective role in autoimmune disease." (PMID 24995020, 2014). "By establishing Treg cells as a critical contributor to the therapeutic effects of systemic IGF-1 delivery in autoimmune disease, our report builds on previous studies documenting decreased Treg numbers and FoxP3 expression in the inflamed pancreas of autoimmune mice." (PMID 25339185, 2014). "Regulation of the members of the FOXP3 interactome may offer opportunities for the development of new treatments for autoimmune diseases, cancer, or infectious diseases." (PMID 24350059, 2013). "Numerous studies in animal models of autoimmunity showed that defects in CD4+CD25+Foxp3+ cells can contribute to the development of autoimmune diseases and that these diseases could be reversed by the adoptive transfer of Treg cells." (PMID 24187560, 2013). "Therapeutic strategies involving the use of HSPs to enhance the availability of Foxp3+ Tregs may be important in autoimmune diseases while in diseases like cancer it may be necessary to inhibit Foxp3 acetylation." (PMID 23573417, 2013). "Notably, Treg cells by expression of the forkhead transcription factor (Foxp3) have a vital role in promoting and maintaining of self-tolerance, thereby preventing chronic inflammatory diseases and autoimmune diseases." (PMID 24098530, 2013). "The development of autoimmune diseases is promoted by deficiency in a special set of regulatory T cells that are crucial in the maintenance of autologous tolerance and are characterized by the expression of CD4, CD25 and FoxP3 (CD4+CD25+FoxP3+ Tregs)." (PMID 23226562, 2012).
autoimmune disease (continued). "We have shown that systemic delivery of autoimmune disease-relevant peptide-major histocompatibility complex class II (pMHCII)-coated nanoparticles (pMHCII-NP) triggers the formation of large pools of disease-suppressing Foxp3– TR1 cells from cognate T-follicular helper (TFH) cell precursors." (PMID 40066448, 2025). "Furthermore, autoimmune diseases like systemic lupus erythematosus (SLE), autoimmune thyroid diseases (AITDs), and type I diabetes (TID) have been linked to polymorphisms in the FOXP3 gene." (PMID 41346162, 2025). "The emergence of AIRE+ and FOXP3+ cells after thymocyte co-culture also raises the possibility that iTECs could support negative selection and Treg generation, which will be an important avenue to explore for applications to autoimmune diseases." (PMID 40855082, 2025). "Moreover, the roles and associations of FoxP3 splice variants with the onset and progression of autoimmune diseases have never been studied before." (PMID 38201281, 2023). "Utilizing a mouse model homologue of FOXP3 deficiency (scurfy mice), the first rescue experiments using adoptive Treg transfer were successfully performed, paving the way for these cells to be applied in therapy of IPEX patients and other autoimmune diseases with dysfunctional FOXP3 expression." (PMID 36562079, 2023). "Interestingly, another study showed a higher level of CTLA-4 in FOXP3- T cells from patients with SLE compared to other autoimmune diseases and healthy controls, but their study indicated that the FOXP3- T cells in SLE patients were unable to control activation and proliferation of effector T cells." (PMID 37497212, 2023). "The discovery of Tregs, a unique, suppressive population characterized by expression of CD25 and Foxp3 with similar phenotype and function in both mouse and humans, generated considerable interest in defining defects in either the number or function of these cells in human autoimmune diseases." (PMID 37350974, 2023). "However, since FOXP3 itself is not mutated in autoimmune diseases other than IPEX, the loss of FOXP3 levels and functional fitness is likely caused by perturbation of the Treg gene regulatory network." (PMID 35773720, 2022). "The high sensitivity of JIA-derived Treg for Th17-inducing stimuli seen in higher level of FoxP3+ cells compared to HC may corroborate the supposed idea of an involvement of Th17-mediated pathways in the pathogenesis of many T cell-mediated autoimmune diseases, such as JIA." (PMID 35410224, 2022). "IPEX syndrome, a multi-organ autoimmune disease from birth, caused by mutations in the transcription factor forkhead box P3 (FOXP3) that result in either a lack of Tregs or impaired Treg function, highlights the importance of Tregs in maintaining peripheral tolerance." (PMID 35979360, 2022). "However, knocking out FOXP3 will cause severe autoimmune diseases or spontaneous breast cancer, leading to a lack of neutralizing antibodies or drugs that specifically block tumor-derived FOXP3." (PMID 36235242, 2022). "Although data about the contribution of FOXP3+ Tregs in the pathogenesis of primary glomerulopathies and systematic autoimmune diseases of native kidneys are scarce, they imply that endogenous FOXP3+ Tregs reduction may negatively impact renal injury progression." (PMID 34336285, 2021). "It has been reported that FOXP3 controls Treg function through co-operation with nuclear factor of activated T cells (NFAT), and deficiency of the FOXP3 gene impairs the suppressor function of Treg cells, which often exacerbates the progression of autoimmune disease." (PMID 33912135, 2021). "Mice lacking Foxp3 expression were seen to develop lethal autoimmune diseases, and humans with a mutation in the Foxp3 gene are known to develop immune dysregulation, polyendocrinopathy, enteropathy, and X-linked syndrome, which is a severe multiorgan autoimmune disease." (PMID 34526990, 2021).
autoimmune disease (continued). "The master lineage-specific transcription factor FOXP3 phenotypically defines the Treg lineage, and genetic deficiency of FOXP3 confers a lack of Tregs and a fatal autoimmune disease known as immunodysregulation polyendocrinopathy enteropathy X-linked in humans and scurfy in mice." (PMID 32522287, 2020). "Some Treg cells may lose Foxp3 expression in autoimmune disease (“ex-Foxp3” cells), others, while maintaining Foxp3 expression, acquire a certain degree of plasticity which is illustrated by secretion of pro-inflammatory cytokines and reduced suppressive function." (PMID 30936873, 2019). "FOXP3 orchestrates a transcriptional network in collaboration with a large number of cofactors, and thus, regulation of the members of the FOXP3 interactome may offer opportunities for the development of new treatments for autoimmune diseases, cancer or infectious diseases." (PMID 29069740, 2017). "MiR-10a is functionally linked to stabilization of FOXP3 in Tregs and interestingly, although miR-10a has not been specifically investigated in relation to HSCT, an inverse correlation between miR-10a and susceptibility to autoimmune disease has been identified." (PMID 28421078, 2017). "The mechanism is not clear yet, but the heterozygosity of Foxp3 polymorphism itself may have unknown but considerable effects on the pathogenesis of various autoimmune disease and also on RRP." (PMID 28298239, 2017). "Expression of the transcription factor Foxp3 is a prerequisite for their suppressive activity, since patients carrying mutations altering the expression or function of Foxp3 may develop IPEX (Immunodysregulation polyendocrinopathy enteropathy X-linked syndrome, a severe autoimmune disease." (PMID 27077371, 2016). "The FOXP3 gene is mutated in scurfy mice, which develop a lethal autoimmune syndrome, and in patients with immune dysregulation polyendocrinopathy, enteropathy, X-chromosome linked syndrome (IPEX) resulting in the breakdown of self-tolerance and the development of autoimmune disease." (PMID 25457307, 2015). "Rare mutations of the FOXP3 gene have been linked with the development of immune dysregulation, polyendocrinopathy, enteropathy, X-linked syndrome (IPEX), leading to organ-specific autoimmune diseases including insulin-dependent diabetes mellitus and various hematological disorders." (PMID 26379673, 2015). "Collectively, the data demonstrating calcitriol enhancement of Ikzf2, FOXP3, and Ctla4 gene expression suggest that vitamin D may significantly influence the emergence of an autoimmune disease phenotype by increasing CD4+CD25+FoxP3+ Treg cells and/or their suppressive function." (PMID 25852682, 2015). "Finally, we addressed whether MSCs could affect the generation of Th1, Th17 and CD4+CD25+Foxp3+ Treg cells in a T-cell-mediated autoimmune disease such as EAE." (PMID 23734780, 2013). "Absence of functional Foxp3 protein due to mutations in the Foxp3 gene results in the development of severe autoimmune disorders as can be observed in the “scurfy” mouse mutant and patients suffering from immune dysregulation, polyendocrinopathy, enteropathy, and X-linked syndrome (IPEX)." (PMID 23737813, 2013). "Thus induction of Foxp3 expression and promotion of Treg cells differentiation might be a promising therapeutic method for the treatment of autoimmunity diseases." (PMID 22591709, 2012). "Hence, the upregulation of Foxp3+ Tregs might be useful for suppressing the activation of autoimmune Th1 and Th17 cells and controlling autoimmune disorders." (PMID 23284794, 2012). "Significant reductions in Foxp3 expression and/or Treg cell function have been observed in patients with several types of human autoimmune diseases, suggesting that defects in Foxp3 expression and/or Treg functioning may precipitate loss of immunological tolerance." (PMID 21994794, 2011).